ACHE (acetylcholinesterase (Yt blood group))
Diseases named in the same sentence as ACHE in open-access papers (continued):
Sharing a sentence is not in itself a finding about the gene and the disease.
memory impairment (continued). "The anxiolytic behavior (open field test and marble burying) in healthy mice, and the Scop-induced memory impairment (object recognition test and Morris water maze (MWM)) were assessed, and the biochemical parameters (malondialdehyde (MDA) and AChE levels) were measured after euthanasia." (PMID 39765648, 2024). "In conclusion, mahanimbine could protect learning and memory impairment in aged mice through attenuation of oxidative stress (MDA), deposition of Aβ1-42, AChE level, and BACE-1 activity while increasing antioxidant (GSH) and ACh levels." (PMID 35053756, 2021). "Mice that received F. mume and scopolamine showed no scopolamine-induced memory impairment and increased activity of AChE." (PMID 25705233, 2015). "The reports have demonstrated that SCO could up-regulate AChE in hippocampus that involved in the SCO-induced learning and memory impairment." (PMID 24505383, 2014). "Absence of significant AChE inhibition and cholinergic toxicity when exposed to chronic low doses of malathion has also been reported in rodents and behavioral effects (e.g., memory impairment) have been attributed to alternative effects, such as mitochondrial dysfunction." (PMID 36267428, 2022). "Umbelliferone did not improve the memory impairment induced by LPS administration, which may be due to lower inhibition potential against AChE level noticed in in vitro studies." (PMID 33579030, 2021).
diabetes (77 papers, 2009 to 2025). "The AChE enzyme is linked to AD development, while α-glucosidase and α-amylase are critical targets in diabetes management." (PMID 39943027, 2025). "In the present study, among individuals with diabetes, acute exposure to AChE inhibitor insecticide was associated with a twofold increased risk of pancreatic cancer." (PMID 41149448, 2025). "These enzymes are linked to diabetes-induced neurodegeneration by driving processes such as cholinergic deficiency (AChE), amyloid plaque formation (BACE-1), inflammation and oxidative stress (DPP-4), and tau pathology (GSK-3β)." (PMID 39766390, 2024). "It is suggested that the cause of inhibition of AChE synthesis is inadequate permeation of glucose across the surface membrane during diabetes." (PMID 20336201, 2009). "In this large nationwide cohort study, acute exposure to AChE inhibitor insecticide was significantly associated with an increased risk of pancreatic cancer, with particularly elevated risks among women and individuals with diabetes mellitus." (PMID 41149448, 2025). "It was reported that enhanced pancreatic, cerebral, and cerebellar functioning were associated with the avoidance of diabetes-mediated increases in AChE activity, indicators of oxidative and inflammatory stress, and caspase-3 activity by protocatechuic acid administration." (PMID 40868857, 2025). "This study comprehensively evaluated the bioactive potential of steam-distilled oil of L. usitatissimum (SDOLU) through a series of in vitro assays targeting its antioxidant capacity and inhibitory effects on critical enzymes linked to AD, diabetes, and glaucoma, namely AChE, α-amylase, and hCA II." (PMID 40871536, 2025). "The increase in AChE activity caused by diabetes leads to a reduction in the efficiency of cholinergic neurotransmission due to a decrease in ACh levels in the synaptic cleft, therefore leading to neurological dysfunctions associated with diabetes." (PMID 38683825, 2024). "Cholinesterases (AChE and BuChE) are essential enzymes associated to memorial and cognitive functions, and determined hyperglycemia may activate memory loss, mainly in Type-2 diabetes mellitus." (PMID 36297317, 2022). "Additionally, the enzyme inhibitory effects of EDOA and EDOR were examined against acetylcholinesterase (AChE), α-glycosidase, and α-amylase enzymes, which are associated with common and global Alzheimer’s disease and diabetes mellitus." (PMID 36296499, 2022). "The inhibition effect of Magnofluorine was examined against enzymes, such as acetylcholinesterase (AChE), α-glycosidase, butyrylcholinesterase (BChE), and human carbonic anhydrase II (hCA II), which are linked to global disorders, such as diabetes, Alzheimer’s disease (AD), and glaucoma." (PMID 36144638, 2022). "Inhibition of AChE at the incretin pathway has been implicated with diabetes mellitus." (PMID 29929492, 2018). "Reduced AChE activity in diabetes has been previously reported, with studies indicating that hyperglycemia disrupts ACh metabolism, leading to synaptic dysfunction and CI." (PMID 40726602, 2025). "Disruptions in the function of certain neurotransmitters, such as AChE, combined with reduced release of BDNF in type 2 diabetes mellitus, significantly heighten the risk of CI in affected individuals." (PMID 40726602, 2025). "The enzymes studied included cholinesterases (AChE and BChE), α-amylase, and α-glucosidase (involved in diabetes)." (PMID 39885008, 2025). "A study on the effects of aqueous extract of S. macrocarpon on cholinesterase activity in alloxan-induced diabetes showed a significant increase in AChE and BChE in diabetic rats." (PMID 40430525, 2025). "The enzyme inhibition assays further underscored the therapeutic potential of these extracts, with significant inhibitory effects on enzymes related to neurodegenerative diseases (AChE, BChE), diabetes (amylase, glucosidase) and skin pigmentation (tyrosinase)." (PMID 39765854, 2024).
diabetes (continued). "The alterations in AChE activity in diabetes are induced by hyperglycemia and lipid peroxidation that triggers brain dysfunction." (PMID 38683825, 2024). "The carbonic anhydrase II (hCA II) enzyme was found to be associated with glaucoma, carbonic anhydrase I (hCA I) with epilepsy, acetylcholinesterase (AChE), and butyrylcholinesterase (BChE) with Alzheimer’s disease, and the α-glycosidase enzyme with diabetes." (PMID 39598187, 2024). "Our findings indicate that AChE levels rose following diabetes induction; however, a 30-day SITG treatment effectively countered this increase, supporting improved cholinergic function in the rat brain." (PMID 39766390, 2024). "Key clinical enzymes involved in neurodegenerative diseases AChE and BChE, diabetes (α-amylase and α-glucosidase) and skin whitening (tyrosinase) were also assayed." (PMID 36770677, 2023). "Treatment with Murraya koenigii extracts significantly prevented the diabetes-induced increase in AChE activity (p < 0.001), which was comparable to the standard donepezil hydrochloride treated group." (PMID 36937470, 2023). "Quercetin reduced the activity of AChE in the synaptosome, cerebral cortex, hippocampus, and striatum of the brain tissue on streptozotocin-induced diabetes rat model." (PMID 35607702, 2022). "The finding of the current research work shows the devastating AChE, BChE, α-amylase, and α-glucosidase potentials of these compounds and reveals their central role in AD and diabetes." (PMID 35942378, 2022). "Several tissues show considerable differences in total AChE activity in diabetes reflecting the dysfunction of the cholinergic system during this disease." (PMID 33708999, 2021). "This flavonoid was responsible for the antioxidant activities and inhibitory activities against the key enzymes controlling diabetes (α-glucosidase and α-amylase) and AD (AChE, BChE, and BACE-1)." (PMID 32887386, 2020). "The activity level of AChE was significantly increased in the brain of diabetes- induced rats versus control (3.3-fold)." (PMID 28505155, 2017). "A recent study reported that inhibition of AChE by galantamine delayed the onset of diabetes in NOD mice." (PMID 27790217, 2016). "AChE activity in the discrete regions of the brain of rats decreased significantly (P<0.01, 0.05 and 0.05 respectively) in diabetes." (PMID 20336201, 2009). "Acute AChE inhibitor insecticide exposure may therefore exacerbate diabetes-related metabolic disturbances, fostering a microenvironment conducive to pancreatic cancer development." (PMID 41149448, 2025). "In these studies, prevention of memory impairments by quercetin against the toxicity of cadmium and in STZ-induced diabetes was partially attributed to the improvement of acetylcholinesterase (AChE) activity in brain structures such as the cerebral cortex and hippocampus." (PMID 40722302, 2025). "Protocatechuic acid (PCA), a main physiologically active substance of KRPBE, protected diabetes-induced neurotoxicity and behavioral disorders by inhibiting the activity of AChE and inflammatory response in cerebral and cerebellar tissues in a diabetic rat model." (PMID 36039041, 2022). "Additionally, cholinergic stimulation by AChE inhibitors can modulate the immune response to autoantigens in different animal models of diabetes." (PMID 29616040, 2018). "In summary, our study showcased a probable association between plasma OP residues and diabetes with no significant changes in plasma AChE." (PMID 28115022, 2017). "Given the central role of T cells and macrophages in the development of T1D and the existence of cholinergic innervation in the pancreas, we investigated the potential immunomodulatory effect of AChE inhibition on the development of diabetes using the MLD-STZ mouse model." (PMID 27790217, 2016).
diabetes (continued). "In order to investigate the potential effect of AChE inhibition on experimental diabetes, C57BL/6 mice were pretreated daily with paraoxon or saline for 3 weeks, and then given MLD-STZ (or saline), as described in the Section “Materials and Methods” and followed for the development of hyperglycemia." (PMID 27790217, 2016). "The decrease in the activity level of AChE in diabetes observed may be a reflection of the type of electrical change in the nervous tissue on inducing alloxan diabetes." (PMID 20336201, 2009). "Furthermore, in AD preclinical models, troxerutin inhibited AChE activity and stimulated the PI3K/Akt pathway, demonstrating its ability to target the key molecular mechanisms underlying the cognitive dysfunction in diabetes." (PMID 38137892, 2023). "In addition, myricetin inhibited AChE activity and enhanced memory functions by protecting hippocampal neurons in a rat model of AD, which may suggest its potential against diabetes-induced cognitive decline." (PMID 38137892, 2023). "In addition, the inhibitory potential of the extract against the key enzymes responsible for world-alarming diseases like neurodegenerative disorder (acetylcholinesterase (AChE) and butyrylcholinesterase (BChE)), diabetes (α-glucosidase and α-amylase), and skin problems (tyrosinase) were estimated." (PMID 33406643, 2021). "However, the efficacy of AChE inhibitors in AD was affected by various factors, including antipsychiatric agents for behavior and psychiatric syndromes, other systemic disorders, hypertension, diabetes, and so on." (PMID 26120358, 2015). "After SITG treatment, AChE levels were significantly reduced in the T2DM + SITG10 (4.671 ± 0.160; p < 0.001) and T2DM + SITG30 (4.433 ± 0.183; p < 0.001) groups in diabetes rats, restoring them to levels comparable to control animals." (PMID 39766390, 2024). "This study investigated phenolics, especially isoflavones, and inhibitory activities against the key enzymes relevant to the control of obesity (lipase), diabetes (α-amylase, α-glucosidase and DPP-IV) and AD (AChE, BChE and BACE-1)." (PMID 36496713, 2022). "Next, the levels of expression of NNCS components (M2AChR, AChE, CHT1, ChAT, VAChT) and GLUT-4 were determined at the three stages of diabetes." (PMID 33618724, 2021). "Results showed that AChE and BDNF levels were significantly decreased in SMG of the untreated diabetes rats compared to the control group." (PMID 34987398, 2021). "With the progression of diabetes, there was downregulation of other NNCS components VAChT and AChE, along with reduced GLUT-4 and cardiac glucose content." (PMID 33618724, 2021). "In diabetes, chronic hyperglycemia induces oxidative stress and neuroinflammation, leading to a reduction in BDNF expression and alterations in AChE activity, both of which contribute to memory deficits and impaired executive function." (PMID 40726602, 2025). "Also, Also, its inhibitory effects chestnut's water extract on some key and metabolic enzymes, including AChE (IC50: 0.084 μg/mL), BChE (IC50: 0.152 μg/mL), and α‐glycosidase (IC50: 0.473 μg/mL) related to diabetes and AD are very important." (PMID 40501503, 2025). "In addition, C. maxima albedo extract exhibited wide ranges of inhibitory properties against enzymes, which are drug targets for the treatment of AD (AChE, BChE, and BACE-1), obesity (lipase), and diabetes (α-glucosidase and α-amylase)." (PMID 37241861, 2023). "Moreover, ART/Met preserved parasympathetic innervation (AChE and BDNF expression) in SGs to alleviate diabetes-induced hyposalivation likely through rescuing central SSN damage." (PMID 34987398, 2021). "Moreover, ART/Met treatment preserved parasympathetic innervation (AChE and BDNF) in SGs to alleviating diabetes-induced hyposalivation likely through rescuing central SSN damage." (PMID 34987398, 2021).
Parkinson disease (73 papers, 2011 to 2025). A progressive degenerative disorder of the central nervous system characterized by loss of dopamine producing neurons in the substantia nigra and the presence of Lewy bodies in the substantia nigra and locus coeruleus. "Our study assessed seed oils’ in vitro neuroprotective potential from borage, calophyllum, and prickly pear, specifically targeting AChE, BChE, and tyrosinase, enzymes associated with Alzheimer’s and Parkinson’s disease." (PMID 40563295, 2025). "A decrease in AChE activity, as seen in neurodegenerative diseases like Parkinson's disease (PD), is often linked to impaired cholinergic neurotransmission and cognitive decline." (PMID 39628974, 2024). "Excessive use of organophosphorus pesticides can cause the inhibition of acetylcholinesterase (AChE) activity and the accumulation of neurotransmitter acetylcholine, eventually leading to the incidence of Alzheimer’s and Parkinson’s diseases." (PMID 36354464, 2022). "The polymorphism of the PON1 C-108T promoter region and the AChE deletion (ΔAChE) were associated with Parkinson’s development by approximately two times." (PMID 33374313, 2020). "Acetylcholinesterases (AChE) are implicated in diseases such as Alzheimer’s disease, senile dementia, Parkinson’s disease, ataxia and myasthenia gravis." (PMID 22489144, 2012). "In contrast, AChE inhibition is often associated with neurotoxicity; it also forms the basis of therapeutic strategies for neurodegenerative disorders, such as Alzheimer’s and Parkinson’s disease." (PMID 40807427, 2025). "Neurologically associated disability, such as Parkinson’s disease, Alzheimer’s disease (AD), and other cognitive losses, is due to defective cholinergic neurotransmission, caused by the lytic action of acetylcholinesterase (AChE) and butyrylcholinesterase (BChE)." (PMID 41304978, 2025). "The modulation of enzymes such as AChE can positively influence neurotransmission in neurodegenerative patients since in many diseases such as Alzheimer's and Parkinson's, intense and dense protein neurofibrillary tangles are formed in the synaptic clefts." (PMID 36100636, 2022). "In neural human diseases, the AChE reduction is the most important effect for the treatment of diseases, such as Parkinson’s and Alzheimer’s." (PMID 36009226, 2022). "AChE inhibitors are used to treat Alzheimer’s and Parkinson’s diseases and cholinergic agonist treatments have shown to improve memory function." (PMID 33602141, 2021). "Both AChE and BChE are crucial in the treatment of neurodegenerative disorders such as Myasthenia gravis, Alzheimer and Parkinson’s disease, since generally all drugs in use act by inhibiting AChE and BChE activity." (PMID 28573890, 2017). "Until now, inhibition of acetylcholinesterase (AChE) has served as a strategy for the treatment of AD, senile dementia, ataxia, and Parkinson’s disease." (PMID 26400617, 2015). "Acetylcholinesterase (AChE) inhibitors have been considered promising tools to treat progressive degenerative neurologic disorders (Alzheimer disease and Parkinson's disease)." (PMID 25690289, 2015). "COS also mediate the inhibition of some important enzymes such as β-secratase, prolyl endopeptidase (PEP) and acetylcholinesterase (AChE) which are involved in neurodegenerative diseases such as Alzheimer's and Parkinson's." (PMID 24957872, 2011). "Similar AChE suppression occurs in Alzheimer’s and Parkinson’s diseases." (PMID 41440141, 2025). "The study hypothesized that SHE possesses antioxidants that could mitigate Parkinson’s symptoms by influencing α-synuclein, acetylcholinesterase (AChE), TNF-α, and IL-1β." (PMID 38551975, 2024). "Usnic acid also interacted with AChE in a mouse model of Parkinson’s disease." (PMID 39519391, 2024). "Inhibition of AChE and BChE may be helpful in the treatment of Alzheimer’s disease; similarly, Parkinson’s disease can also be fought by inhibiting the action of the tyrosinase enzyme." (PMID 38671929, 2024).
Parkinson disease (continued). "Acetylcholinesterase and butyrylcholinesterase (AChE and BChE) are involved in modulating cholinergic signaling, but their roles in Alzheimer’s and Parkinson’s diseases (AD and PD) remain unclear." (PMID 36117917, 2022). "However, the AChE activity is increased in frontotemporal dementia with parkinsonism-17 human tau transgenic mice." (PMID 34975454, 2021). "In support of this hypothesis, AChE inhibitors have shown benefits in Alzheimer’s and Parkinson’s disease patients, and reduced mitophagy contributes to mitochondrial dysfunction in many neurodegenerative diseases, including A-T." (PMID 29338042, 2018). "Both AChE and BChE are crucial in the treatment of neurodegenerative disorders such as myasthenia gravis, Alzheimer and Parkinson’s disease, since so far the most successful approach in treating these disorders has been the use of cholinesterase inhibitors that target primary AChE." (PMID 30289893, 2018). "As far as we know, N-[2-(substituted-phenyl)ethyl]-4-quinazolinamines have been reported as acetyl- and butyrylcholinesterase inhibitors (AChE IC50 = 6.2 μM; BuChE IC50 = 14.1 μM) for the treatment of Parkinson disease and inhibitors of NFκB." (PMID 33435251, 2021). "Indeed, AChE and BChE inhibition may slow neurodegeneration in AD and Parkinson's disease (PD)." (PMID 29344419, 2017). "This prodrug has been shown to inhibit both AChE and BuChE, which, by decarbamylating this molecule, releases a phenol derivative of rasagiline, a monoamine oxidase B inhibitor (MAO-B), which is also used in Parkinson’s disease for its neuroprotective effect." (PMID 37896142, 2023). "Researchers found that T2FA, an AChE inhibitor, reduced 6-OHDA-induced apoptosis in PC12 cells and so might be used to change the etiology of Parkinson's disease (PD)." (PMID 36035218, 2022). "The authors suggested that hereditary interaction at the AChE and PON1 locus may increase the occurrence of insecticide-induced Parkinson’s disease." (PMID 33374313, 2020). "Although AChE activity reportedly decreases in Parkinson's disease, the relationship between BChE activity and Parkinson's disease had not been clearly performed." (PMID 28840123, 2017). "Paraoxon-induced AChE inhibition can aggravate experimental Parkinsonism triggered by MPTP in mice, suggesting paraoxonase may play a role in defending against Parkinson etiologic factors." (PMID 25210784, 2014). "Telfairia occidentalis's inhibitory actions against the enzymes acetylcholinesterase (AChE) and monoamine oxidase (MAO) offer encouraging neuroprotective potential, particularly when it comes to treating neurodegenerative diseases like Alzheimer's and Parkinson's." (PMID 41459082, 2025).